LINC00492 (long independently transcribed non-coding RNA 492)
Gene: Long non-coding RNA gene on chromosome 5 (102,581,368 to 102,617,589, forward strand). Ensembl gene ENSG00000250958.
Diseases named in the same sentence as LINC00492 in open-access papers:
LINC00492 is named in the same sentence as 1 disease in open-access papers, as found by Europe PMC text mining. Sharing a sentence is not in itself a finding about the gene and the disease.
LINC00492 shares sentences with these, for which no sentence is quoted: cancer (1 paper).